RNF5P1 (ring finger protein 5 pseudogene 1)
Gene: Processed pseudogene on chromosome 8 (38,600,661 to 38,601,200, reverse strand). Ensembl gene ENSG00000253570.
Diseases named in the same sentence as RNF5P1 in open-access papers:
RNF5P1 is named in the same sentence as 2 diseases in open-access papers, as found by Europe PMC text mining. Sharing a sentence is not in itself a finding about the gene and the disease. The quoted sentences say what the papers report.
ischemic stroke (1 paper, 2024). A stroke disorder caused by obstruction of blood flow to the brain, due to thrombotic (local blood clot formation) or embolic (due to a blood clot or other material traveling from another site) event. "Higher expression of RNF5P1 correlates with an increased risk of ischemic stroke, highlighting its potential role in stroke pathogenesis." (PMID 38952424, 2024).
RNF5P1 also shares sentences with these, for which no sentence is quoted: Stroke (1 paper).